SPADH (spermadhesin family member)
Gene: Protein-coding gene on chromosome 10 (122,672,850 to 122,679,494, forward strand). Ensembl gene ENSG00000286135.
Genetic constraint (gnomAD): Loss-of-function variants: 0 observed, 1.22 expected, observed/expected ratio (o/e) 0, 90% interval 0 to 1.65. That is too few expected variants to judge how well the gene tolerates losing a copy. Missense variants: 13 observed, 18.34 expected, observed/expected ratio (o/e) 0.71, 90% interval 0.46 to 1.13. Synonymous variants: 3 observed, 7.26 expected, observed/expected ratio (o/e) 0.41, 90% interval 0.19 to 1.07.
Homologues: Orthologues: macaque SPADH (92% identical), pig AWN (46% identical), pig PSP-I (43% identical), pig PSP-II (36% identical), pig SPMI (34% identical).
Diseases named in the same sentence as SPADH in open-access papers:
SPADH is named in the same sentence as 3 diseases in open-access papers, as found by Europe PMC text mining. Sharing a sentence is not in itself a finding about the gene and the disease.
SPADH shares sentences with these, for which no sentence is quoted: cancer (1 paper); infection (1); tumor (1).